MALAT1 (metastasis associated lung adenocarcinoma transcript 1)
Diseases named in the same sentence as MALAT1 in open-access papers (continued):
Sharing a sentence is not in itself a finding about the gene and the disease.
cancer (continued). "The long noncoding RNA MALAT1, which is involved in splicing speckles and used as a marker in many late-stage cancers, was noticeably downregulated, while several other abundant noncoding RNAs were strongly upregulated." (PMID 26407100, 2015). "Elevated MALAT1 expression was indicative of poor prognosis in patients with various types of cancer." (PMID 26420912, 2015). "We successfully applied this strategy, in combination with integration of a selection marker (Green Fluorescent Protein, GFP) to silence the lncRNA Malat1 in human cancer cells." (PMID 25580533, 2015). "MALAT-1 has been primarily studied for its role in cancer cells migration, invasion and metastasis, but, in addition, it plays an important role in cell cycle progression." (PMID 25428918, 2014). "This is an important mechanism of action of ZEB2-AS1 and MALAT1 lncRNAs, which exerts potent pro-metastatic function in several cancer cell types." (PMID 24346158, 2014). "B-MYB is overexpressed in many cancers and its expression and/or RNA processing is controlled by MALAT-1." (PMID 25428918, 2014). "MALAT1 was shown to be detectable in the cellular fraction of peripheral human blood, showing different expression levels between cancer patients and cancer-free controls." (PMID 24313945, 2013). "MALAT1, an mRNA splicing mediator, is upregulated in several human cancers and contributes to cancer cell proliferation." (PMID 23880895, 2013). "Although the oncogenic role of MALAT1 in different cancers has been demonstrated by correlational and functional studies, the molecular mechanisms underlying its activities in regulating gene expression and RNA splicing remain undetermined." (PMID 24013378, 2013). "MALAT1 is overexpressed in several cancer types, including lung, breast, colon and hepatocarcinoma, and overexpression of MALAT1 in various cell lines enhanced cell proliferation whereas in nude mice, increased levels of MALAT1 promoted tumor formation." (PMID 23555285, 2013). "We previously demonstrated that in cancer cells, MALAT1 modulates alternative splicing of pre-mRNAs and regulates the cellular activity of SR splicing factors." (PMID 23555285, 2013). "Candidate lncRNAs like NEAT2 and MALAT1 have been studied in detail with their relations with metastasis in cancers." (PMID 23846593, 2013). "MALAT1 is widely expressed in normal human tissues and is found to be upregulated in a variety of human cancers of the breast, prostate, colon, liver and uterus." (PMID 23443164, 2013). "Metastasis-associated lung adenocarcinoma transcript 1 (MALAT1), also known as nuclear-enriched abundant transcript 2 (NEAT2), is one of the first identified cancer-associated lncRNAs." (PMID 24013378, 2013). "We and others have previously reported that MALAT1-depleted cancer cells show increased levels (including the dephosphorylated pool) of SRSF1." (PMID 23555285, 2013). "In general, human fibroblasts with a finite life span showed proliferation defects (WI-38, IMR-90 cells), whereas cancer or immortalized cell lines displayed a wide spectrum of abnormalities upon MALAT1 depletion." (PMID 23555285, 2013). "Recent studies have also demonstrated that depletion of MALAT1 impairs proliferative and invasive properties of cancer cells." (PMID 23555285, 2013). "In this study, a significant downregulation of MALAT1 in NSCLC patients in comparison to cancer-free controls was shown." (PMID 24313945, 2013). "NEAT2 (MALAT-1) is a marker of diverse human carcinomas, and a predictor of survival and metastasis across multiple cancer types." (PMID 23577021, 2013). "Several lncRNAs (e.g., MALAT1, HOTAIR, and ANRIL) are associated with human diseases, including cancer." (PMID 23109937, 2012). "MALAT1 is upregulated in a variety of other human cancers including breast, colon, prostate, and liver cancer." (PMID 22852089, 2012).
cancer (continued). "MALAT1 is an lncRNA that has attracted considerable attention in recent years due to its crucial involvement in diverse biological processes and diseases, particularly cancer." (PMID 41584724, 2026). "Blocking MALAT-1 in the CCL5/MALAT-1/Snail axis prevented Snail overexpression from causing CCL5-induced migration and invasion, demonstrating the vital of this axis in the DC-dependent cancer development." (PMID 39944836, 2025). "Investigating the molecular pathways involving SOX2, PIWI proteins, and MALAT1 could provide deeper insights into their role in cancer progression, potentially paving the way for targeted therapeutic strategies." (PMID 40674376, 2025). "Both GAS5 and MALAT1 have been extensively studied in the field of cancer research." (PMID 40331955, 2025). "Similarly, MALAT1 has been studied in some cancers, including lung, breast, and hepatocellular carcinoma." (PMID 41181715, 2025). "MALAT1 is a lncRNA crucial in several stages of cancer initiation and progression." (PMID 41013839, 2025). "MALAT1 plays different roles in bone metastasis, depending on the type of cancer." (PMID 40872531, 2025). "Adeno-associated virus (AAV)-mediated delivery holds promise for DMD therapy, supported by precedents in other diseases where AAV vectors delivered lncRNAs like H19 (cancer), Malat1 (vascular disease), and Neat1 (neurological disorders) to achieve therapeutic effects." (PMID 40649811, 2025). "Given that MALAT1 is overexpressed in various types of cancer and is secreted in exosomes, it is tempting to speculate that its overexpression prevents the activation of antitumor T cells." (PMID 40429961, 2025). "MALAT1, NEAT1, and HOTAIR integrate stress signals with chromatin, transcriptional, and post-transcriptional control, and have been separately linked to apoptosis and autophagy in several cancers." (PMID 41373437, 2025). "Malat1, a key lncRNA in cancer and immune cell function that inhibits cytotoxic T cells activation and promote immunosuppressive myeloid cells infiltration, was upregulated in T and NK cells and immunosuppressive BAMs but downregulated in immunosuppressive GAMs, int Mo/Mac and Macrophages." (PMID 40527978, 2025). "MALAT1 expression has been inhibited using CRISPR interference, which was associated with a decrease in the levels of transcription factor NR4A1, whose expression is dysregulated in cancer." (PMID 41181715, 2025). "The MALAT1 RNA is implied to be involved in stress responses and diseases including cancers." (PMID 40966253, 2025). "However, the role of MALAT1 in cancer pathogenesis, progression and dissemination varies by cancer type." (PMID 40783798, 2025). "MALAT1, another oncogenic lncRNA, is highly expressed in various cancers." (PMID 40621472, 2025). "For example, in metastasis-associated lung adenocarcinoma transcript 1 (MALAT1), which is frequently upregulated in cancer, m6 A destabilizes the hairpin stem structure of the transcript and likely controls the function of MALAT1 in splicing and transcription by regulating RNA–protein interactions." (PMID 40382536, 2025). "To investigate whether CricNOTCH1 and/or lncRNA MALAT1 regulate xCT expression via miR-34c modulation, affecting cancer phenotypes such as drug resistance, we performed systematic gain-of-function (GoF) and loss-of-function (LoF) perturbations." (PMID 39846637, 2025). "Furthermore, KEGG enrichment analysis shows that the knockdown of Meis1 and Malat1 affected proteins that play a role in various cancer pathways, which is consistent with their previously reported functions in tumorigenesis." (PMID 39851553, 2025). "Notably, MEG3, MIAT, Malat1, SNHG20, SNHG12, Ftx, Pvt1, Mir9-3hg expression in cancer immune cells was associated with an immunosuppressive phenotype, while H19, SNHG6, Trp53cor1, MiR17hg and MiR142hg were linked to a pro-inflammatory phenotype in cancer." (PMID 40527978, 2025).
cancer (continued). "Although the 3′ end of this gene is widely correlated with cancer progression both in terms of MALAT1 and mascRNA expression, a recent study demonstrated that artificially alternatively transcribed 3′ regions of MALAT1 can prevent retinal oxidative stress from arising in murine models." (PMID 40521240, 2025). "MALAT1 could be transferred from TAMs to cancer cells, while the dual silencing of MALAT1 in tumor cells and TAMs by transferring siRNAs via exosomes significantly enhanced chemosensitivity in the setting of GC." (PMID 40236651, 2025). "It indicates multiple activation mechanisms of MALAT1 in various cancers." (PMID 40783798, 2025). "Quercetin inhibits the expression of MALAT1 in prostate and in breast cancers." (PMID 40282449, 2025). "Here we speculate that the cancer-associated lncRNAs NEAT1 and MALAT1 may modulate A3B activity, possibly by sequestration or serving as suicide substrates." (PMID 39322638, 2024). "Recently, several studies highlighted the immunomodulatory role of MALAT-1 and how it can enable cancer cells to escape immune surveillance by exerting an immunosuppressive effect and regulating the expression of several molecules associated with the tumor microenvironment." (PMID 38201661, 2024). "Malat1 has been reported to acts as an oncogene in various cancers." (PMID 39363237, 2024). "Recent studies have shown that MALAT-1 plays a vital role in the onset and spread of cancer." (PMID 38511067, 2024). "Several studies have discussed the role of MALAT-1 in facilitating chemoresistance in cancer." (PMID 38201661, 2024). "However, studies on the time-dependent modulation of MALAT1 expression and how this alteration in gene expression and chromatin accessibility affect gene-specific mechanisms of transcriptional regulation in cancer are still scarce." (PMID 38791553, 2024). "Collectively, these research findings underscore the substantial involvement of MALAT1 in the complex terrain of cancer evolution and progression, highlighting the need for further investigations to elucidate its specific roles within distinct cancer types." (PMID 39323624, 2024). "Such functions have made lncRNAs central players in the development and progression of numerous diseases, including cancer, where specific lncRNAs like HOTAIR, MALAT1, and HOTAIR have been linked to metastasis, highlighting their potential as therapeutic targets and biomarkers." (PMID 39325172, 2024). "The subnetwork analyses showed that NEAT1, MALAT1, and OIP5-AS1 are associated with genes involved in cancer-related pathways, including the "mTOR signaling pathway," "AMPK signaling pathway", and "PI3K-Akt signaling pathway", as identified in KEGG pathway analysis." (PMID 39246994, 2024). "Indeed, the analysis illustrated that MALAT-1 expression is significantly higher in metastatic samples than in tumor and normal samples, affirming the fundamental role of MALAT-1 in inducing cancer metastasis." (PMID 38201661, 2024). "Similarly, in the experimental dataset, there are several records of MALAT1 regulatory relationships validated in cancer." (PMID 38360815, 2024). "ASO therapeutics have been used to target and regulate the MALAT1 lncRNA in various cancer types." (PMID 38338910, 2024). "Although the overexpression of MALAT1 or TCF12 has been independently linked to poorer prognosis in CRC patients, investigations conducted across different cancer types or patient cohorts may have contradictory results." (PMID 39768127, 2024). "Our analysis reveals that specific lncRNAs, such as MALAT1, HOTAIR, and PVT1, interact with crucial proteins and pathways that govern mitochondrial function and oxidative stress responses, thereby influencing the susceptibility of cancer cells to cuproptosis." (PMID 39325172, 2024). "Preclinical models showed that the inhibition of Malat1 expression may be a promising approach to treating cancers." (PMID 39272802, 2024).
cancer (continued). "In addition, we have used bioinformatics online tools to highlight the disparities in the expression of MALAT-1 between normal and cancer samples using data from The Cancer Genome Atlas (TCGA)." (PMID 38201661, 2024). "This section examines MALAT-1's effects on immune cells and how they may affect the body's ability to fight cancer." (PMID 38511067, 2024). "MALAT1 (metastasis-associated lung adenocarcinoma transcript 1; also known as NEAT2, nuclear-enriched abundant transcript 2) was the first identified and best characterized lncRNA, whose role in the initiation and clinical behavior of different types of cancer has been widely studied." (PMID 38255996, 2024). "On the other hand, MALAT1 plays a significant role in various cancer types." (PMID 38476024, 2024). "Overall, most frequently found lncRNA fusions in cancers involved MALAT1 and PVT1 parts." (PMID 38919532, 2024). "LncRNA MALAT1 has been extensively studied in various cancers, including CRC." (PMID 39471147, 2024). "Therefore, the expression level of MALAT1 can be said to be inconclusive throughout cancer stages and varies in different types of cancer as well as different sites of metastasis." (PMID 39725668, 2024). "Recently, it has been shown that MALAT-1 has a crucial role in cancer cell apoptosis." (PMID 38511067, 2024). "However, further research is needed to fully uncover the role of MALAT-1 in cancer biology and translate these findings into clinical applications." (PMID 38511067, 2024). "Comprehensive studies in larger patient cohorts with detailed genomic analysis are essential to confirm the regulatory roles of NEAT1 and MALAT1, contributing to a comprehensive understanding of how APOBEC3 enzymes promote cancer evolution by causing genome and transcriptome heterogeneity." (PMID 39322638, 2024). "In cancer models, MALAT1 lncRNA is upregulated, as it promotes cell growth and reproduction." (PMID 39199508, 2024). "MALAT1 has emerged as a key contributor to the induction of EMT across diverse cancer types." (PMID 39323624, 2024). "Moreover, in the same cancer entity, it was observed that, post-transcriptionally, MALAT1 molecules can be regulated by miR-101 and miR-217, leading to MALAT1 silencing and suppressing the proliferation of ESCC cells by arresting the G2/M cell cycle." (PMID 38674413, 2024). "For example, MALAT-1 has been discovered to affect cell growth in several cancer types." (PMID 38511067, 2024). "In addition to its involvement in cancer, MALAT1 regulates diverse pathophysiological processes in the cardiovascular system." (PMID 39172906, 2024). "MALAT1 may shield cancer cells from copper-induced stress in the setting of cuproptosis by maintaining Wnt/β-catenin signaling, which promotes cell survival and proliferation." (PMID 39325172, 2024). "MALAT-1 has been shown to work as an oncogene and increase cancer invasiveness and metastasis." (PMID 38201661, 2024). "MALAT-1 induces cancer proliferation, invasion, migration, and metastasis to distant sites." (PMID 38201661, 2024). "Furthermore, MALAT1 exerts its impact on cancer progression by intricately interacting with several oncogenic signalling pathways, including but not limited to the TGF/SMAD, Hippo, JAK/STAT, and Wnt/β-catenin pathways." (PMID 39323624, 2024). "Many studies have identified a link between MALAT1 and an unfavorable outcome in cancer." (PMID 40034935, 2024). "Studies have also reported that exosomal MALAT1 contributes to chemotherapy resistance in cancer." (PMID 39401197, 2024). "Additionally, studies have demonstrated that the increased expression of MALAT1 leads to the inhibition of miR‐218 expression, subsequently promoting cancer cell proliferation, invasion, and metastasis." (PMID 39347925, 2024). "Silencing MALAT-1 reduces cancer migration, invasion, and metastatic properties." (PMID 38201661, 2024).
cancer (continued). "We further functionally evaluated whether increasing MALAT1 expression could enhance the in vitro tumorigenic capabilities of cancer cells." (PMID 38791954, 2024). "Targeting MALAT-1-mediated processes may pave the way for more effective personalized treatments and improved clinical outcomes in cancer patients." (PMID 38511067, 2024). "The biological roles of MALAT1 in cancer have been well studied." (PMID 38639382, 2024). "In addition, SULT2B1 and MALAT1 have been extensively studied in the field of cancer in recent years." (PMID 39525632, 2024). "EMT, a crucial stage in the metastatic process, is the main way MALAT-1 affects cancer propagation." (PMID 38511067, 2024). "A therapeutic that simultaneously reduces the levels of both MALAT1 and MENβ could be advantageous for cancers experiencing an upregulation of MALAT1 and MENβ, such as lung, breast, colorectal and many other cancer types." (PMID 38338910, 2024). "Targeting MALAT-1 induces DNA damage and sensitizes cancer to chemotherapy treatment." (PMID 38201661, 2024). "Furthermore, MALAT-1 downregulation inhibits cancer cell proliferation, invasion, and metastasis in GC cells in vitro and in vivo." (PMID 38201661, 2024). "Preliminary clinical data show that higher NEAT1 and MALAT1 expressions correlate with reduced A3B and increased A3A activities in cancers like breast and lung, suggesting their role in enzymatic balance between A3B and A3A, affecting mutation dynamics and cancer progression." (PMID 39322638, 2024). "Multiple lines of evidence insinuate that MALAT-1 plays a crucial role in cancer by regulating EMT." (PMID 38201661, 2024). "In the realm of cancer biology, MALAT1 emerges as a multifaceted regulator, influencing gene expression, cell proliferation, migration, invasion, and autophagy through an array of mechanisms, notably including miRNA sequestration and the modulation of target gene expression." (PMID 39323624, 2024). "Furthermore, the intricate interplay of MALAT-1 with several essential targets of cancer progression and metastasis renders it a good candidate for therapeutic interventions." (PMID 38201661, 2024). "These discrepancies could be explained by the diverse effects of MALAT1 downregulation on different cancer cells, where genome-wide transcriptomic changes have been reported." (PMID 38791553, 2024). "The very same mechanism of destabilization of MALAT1 occurring in cancers may be active in AD presentation." (PMID 39199508, 2024). "The up-regulated level of MALAT1 is often used as a prognostic marker for various cancer types." (PMID 38328782, 2024). "Extensive research has established a compelling connection between MALAT1 and the onset of cancer." (PMID 39323624, 2024). "Supported by TCGA data, NEAT1 and MALAT1 expressions could predict A3B activity, aiding in evaluating cancer progression and response to A3B-targeted therapies." (PMID 39322638, 2024). "This ambiguity implies that MALAT-1 has a pleiotropic effect in cancer cells." (PMID 38201661, 2024). "MALAT1 also promotes cell migration and invasion, which are crucial steps in cancer metastasis." (PMID 39471147, 2024). "For instance, knocking out NEAT1 and MALAT1 from the promoter region inhibits cancer metastasis." (PMID 39257589, 2024). "The mode of MALAT1 action in cancer is multifold since it interacts with an array of microRNAs, as well as with mRNA and proteins, leading to significant changes within signaling pathways that, in turn, more or less contribute to the cancer phenotype." (PMID 38674413, 2024). "As the full name of MALAT1 suggests, this lncRNA influences cancer metastasis." (PMID 38674413, 2024). "The long non-coding RNA (lncRNA) MALAT1 is a regulator of oncogenesis and cancer progression." (PMID 37235843, 2023). "An analysis of 89 pathways in 64 different cancers has revealed the presence of MALAT1." (PMID 38045858, 2023).